VWA3A (von Willebrand factor A domain containing 3A)
Synonyms: FLJ46765; FLJ40941
Tractability: Antibody: UniProt places it where antibodies can reach, with high confidence; UniProt predicts a signal peptide or a membrane-spanning region; its Gene Ontology location is reachable by antibodies, with medium confidence. PROTAC: ubiquitination databases record sites on it.
Gene: Protein-coding gene on chromosome 16 (22,092,528 to 22,156,964, forward strand). Ensembl gene ENSG00000175267.
Subcellular location: Secreted
Gene Ontology:
Cellular component: extracellular region
Genetic constraint (gnomAD): Loss-of-function variants: 130 observed, 148.61 expected, observed/expected ratio (o/e) 0.87, 90% interval 0.76 to 1.01. The upper end of that interval is the gene's LOEUF score, 1.01, which puts it in group 4 of 6, group 1 being the genes least tolerant of losing a copy. Missense variants: 1,274 observed, 1,429.9 expected, observed/expected ratio (o/e) 0.89, 90% interval 0.85 to 0.93. Synonymous variants: 462 observed, 533.99 expected, observed/expected ratio (o/e) 0.87, 90% interval 0.8 to 0.93.
Homologues: Orthologues: chimpanzee VWA3A (99% identical), macaque VWA3A (95% identical), rabbit VWA3A (80% identical), dog VWA3A (79% identical), pig VWA3A (78% identical), guinea pig VWA3A (75% identical), rat Vwa3a (72% identical), mouse Vwa3a (71% identical), tropical clawed frog vwa3a (50% identical), zebrafish vwa3a (14% identical). Paralogues in human: ITIH1 (12% identical), ITIH3 (11% identical), ITIH4 (11% identical), VWA3B (11% identical), ITIH2 (11% identical), VWA5B1 (10% identical), ITIH5 (10% identical), PARP4 (10% identical), VWA5A (10% identical), VWA5B2 (10% identical), ITIH6 (10% identical).
Diseases named in the same sentence as VWA3A in open-access papers:
VWA3A is named in the same sentence as 1 disease in open-access papers, as found by Europe PMC text mining. Sharing a sentence is not in itself a finding about the gene and the disease.
VWA3A shares sentences with these, for which no sentence is quoted: progressive supranuclear palsy (1 paper).